IFNG (interferon gamma)
Diseases named in the same sentence as IFNG in open-access papers (continued):
Sharing a sentence is not in itself a finding about the gene and the disease.
melanoma (continued). "Knockdown of FTO sensitizes melanoma cells to interferon gamma (IFNγ) and sensitizes melanoma to anti-PD-1 treatment in mice, depending on adaptive immunity." (PMID 31239444, 2019). "IL-12-responding ILC1s induce a signature TME characterized by strong upregulation of IFNγ and type I-associated chemokine receptors (CXCR6, CCR5, CXCR3, and CCR1) to recruit tumor invading Rorcfm+ILCs in a mouse model of melanoma." (PMID 32117199, 2019). "Non IL32-expressing differentiated melanoma cell lines exposed to TNFα or IFNγ can be induced to express the three predominant isoforms (α, β, γ) of IL32." (PMID 30953519, 2019). "Only IFNβ is expressed in untreated melanoma cells; however, levels of secreted IFNγ and TNFα become significantly increased in the sera of melanoma patients under targeted therapy." (PMID 30850015, 2019). "FTO knockdown did indeed sensitize melanoma cells to IFNγ-induced growth inhibition and cell killing." (PMID 31239444, 2019). "Consistently we found that IFNγ downregulates FTO in melanoma cells, and FTO mediates resistance to melanoma cell killing by IFNγ through its m6A demethylase activity and downstream targets PD-1 (PDCD-1), CXCR4, and SOX10." (PMID 31239444, 2019). "Mechanisms of acquired resistance to checkpoint inhibitors include loss of IFNγ-transducing signaling pathways JAK1 and JAK2, loss of antigen presentation (B2M) and activation of the PTEN/PI3K pathway in pembrolizumab-treated melanoma patients." (PMID 31647026, 2019). "Direct STAT3 targeting in melanoma cell lines sufficed to modulate these crosstalks and enhanced antitumor activity through increasing interferon gamma (IFNγ) levels, mature dendritic cells, and CD8+ T cells." (PMID 31569642, 2019). "T cell-secreted IFNγ was reported to mediate the induction of PD-L1 expression in melanoma microenvironment." (PMID 30948928, 2019). "ILC1s in response to IL-12, a potent antitumor cytokine, produce the effector cytokines, IFNγ and TNFα, to limit tumor growth in a melanoma mouse model." (PMID 32117199, 2019). "In this scenario, CD160 deficient NK cells showed in melanoma and RMA-S lymphoma tumor models a defect in tumor control due to impaired IFNγ production." (PMID 30483269, 2018). "Our results demonstrate that melanoma responses to IFNγ are heterogeneous, frequently downregulated in immune checkpoint inhibitor-naïve melanoma and potentially predictive of response to immunotherapy." (PMID 29977240, 2018). "Of the 38 melanoma cell lines tested, three showed increasing cell death in response to IFNγ, with greater than 10% increase in sub G1." (PMID 29977240, 2018). "Expression of IFNγ-target proteins at baseline and post-stimulation with IFNγ in 39 melanoma cell lines." (PMID 29977240, 2018). "Chi3l1-deficient T cells were differentiated into T cells with Th1-prone phenotypes with hyper-responsive to IFNγ signaling and melanoma lung metastasis was significantly reduced in the mice with both Chi3l1 total knock out and CD4−Cre system." (PMID 29403003, 2018). "In this study, we investigated the response of a large panel of human melanoma cells to IFNγ stimulation." (PMID 29977240, 2018). "Attenuation of IFNγ-induced PD-L1 expression in melanoma cells was proven to happen via down-regulation of the Jak/STAT/IRF-1 signaling pathway, while activation of Jaks led to PD-L1 up-regulation in hematopoietic tumor cell lines and primary tumor cells." (PMID 30356906, 2018). "It is worth noting that of the 26 melanoma cell lines displaying incomplete induction of the 5 target proteins, 8 showed cell cycle distribution changes in response to IFNγ treatment." (PMID 29977240, 2018). "We show that incomplete IFNγ signaling occurs in almost 70% of immunotherapy-naïve melanoma, and previous reports have confirmed that pre-existing alterations affecting IFNγ signaling have the potential to confer resistance to immune checkpoint inhibitors." (PMID 29977240, 2018).
melanoma (continued). "This, too, is consistent with previous reports that IDO1 expression increases in response to IFNγ produced by CD8+ T cells within the tumor microenvironment in melanoma." (PMID 29805749, 2018). "Recently, Mo et al43 reported that IFNγ induced melanocyte and melanoma cells to express human CTLA‐4 gene, which was dependent on IFNGR/STAT1 signaling pathways." (PMID 30039553, 2018). "Up-regulation of PD-L1 on melanoma cells is believed to result from interferon gamma (IFN-γ) release by T cells that interact with the tumor." (PMID 30240750, 2018). "Overall, exposure of melanoma cells to IFNγ induced heterogeneous levels of all target molecules, and induction did not appear to depend on genotype in cutaneous melanomas for PD-L1, PD-L2, HLA-ABC, and NGFR." (PMID 29977240, 2018). "Only 13/39 (33%) of the melanoma cell lines tested responded to IFNγ with potent induction of all targets, indicating that downregulation of IFNγ signaling is common in melanoma." (PMID 29977240, 2018). "In conclusion, our study demonstrates that expression analysis of IFNγ targets pre- and post-IFNγ stimulation can identify incomplete IFNγ pathway activity in melanoma cells." (PMID 29977240, 2018). "Here, we report that in response to the anti-tumor, pro-inflammatory cytokine interferon-gamma, melanoma cell expression of LAMP2C mRNA significantly increased." (PMID 30211163, 2018). "Analysis of the IFNγ target proteins, HLA-ABC, HLA-DR, NGFR, PD-L1, and PD-L2, in a panel of 39 melanoma cell lines revealed that IFNγ stimulated cell surface expression of all five markers in only 13 melanoma cell lines tested." (PMID 29977240, 2018). "We also examined the impact of IFNγ treatment on cell cycle progression in our panel of melanoma cells using flow cytometry." (PMID 29977240, 2018). "In keeping with this, expression of a 10-gene IFNγ signature was initially interrogated in baseline tumor biopsies from 19 melanoma patients treated with anti-PD-1." (PMID 29968076, 2018). "Deletion of Chi3l1 in T cells in mice show reduced melanoma lung metastasis with increased IFNγ and TNFα-producing T cells in the lung." (PMID 29403003, 2018). "Expression of a 28-gene expanded immune signature that incorporated the 10 IFNγ genes as well as T cell and antigen presentation molecules was further validated in a separate cohort of 62 melanoma patients." (PMID 29968076, 2018). "B16F10 melanoma cells are known to show low MHC II expression under standard culture conditions but to upregulate expression of IAb upon IFNγ treatment." (PMID 28301575, 2017). "But evidence from different in vivo studies suggests that the anti-proliferative and pro-apoptotic activity of IFNγ on melanoma cells contributes essentially to the efficacy of T-cell-mediated anti-tumour immunity." (PMID 28561041, 2017). "Chromosomal alterations and subsequent inactivating mutations in genes of the IFNγ signalling cascade, most often JAK1 or JAK2, protect melanoma cells from anti-tumour IFNγ activity." (PMID 28561041, 2017). "These melanoma cells were treated with glycosylated IFNγ, alone or in combination with galectin antagonist LacNAc." (PMID 28986561, 2017). "Our studies in the three melanoma patient models identified allelic JAK1 and JAK2 losses as initial genetic alteration predisposing to IFNγ-resistance development." (PMID 28561041, 2017). "Similar to Ma-Mel-54, multiple cell lines were established from distinct melanoma metastases of patient Ma-Mel-61 collected over a period of 2.5 years, allowing us to follow the development of IFNγ resistance in the course of disease." (PMID 28561041, 2017). "Accordingly, analyses on TCGA melanomas revealed a strong association between patient survival and elevated mRNA levels of STAT1 and its downstream target IRF1, indicating IFNγ-dependent pathway activation." (PMID 28561041, 2017).
melanoma (continued). "Studies show surgical stress results in a reduction in the number of CD8+ T cells that produce cytokines (IFNγ, TNFα, and Granzyme B) in response to TAA (adenovirus expressing melanoma tumor-associated antigen)." (PMID 29201900, 2017). "The detection of IFNγ-resistant melanoma metastases in our patient cohort led us to assess the presence of alterations in type II IFN signalling pathway components in independent sample collections." (PMID 28561041, 2017). "Our findings suggest sequential screening of tumour biopsies for genetic defects in the IFNγ signalling cascade will aid therapeutic decision-making in patients with advanced melanoma." (PMID 28561041, 2017). "Immune checkpoint inhibitors are now routinely used in treatment of melanoma, and these antibodies have the capacity to induce IFNγ at the tumor site." (PMID 26885372, 2016). "In both cases the percentage of activated T-lymphocytes (secreting TNFα) was increased following incubation of melanoma cells with IFNγ." (PMID 26885372, 2016). "In vitro, an increase in IFNG induces many melanoma cell lines to upregulate MHC class I expression." (PMID 28101055, 2016). "Treatment of melanoma cells with both PR-924 and IFNγ also slightly enhanced T-lymphocyte responses to the NY-ESO-1124–133, however not significantly or to the levels observed under steady state conditions." (PMID 26885372, 2016). "A unique subset of melanomas are capable of expressing MHC-II under basal or IFNγ-stimulated conditions." (PMID 26822383, 2016). "We found that our melanoma cells lines had increased sensitivity to PR-924 following co-incubation with IFNγ." (PMID 26885372, 2016). "We previously observed that in a diverse collection of melanoma cell lines, patterns of HLA-DR expression were (i) constitutively high, (ii) heterogeneous, but inducible by IFNγ, or (iii) constitutively off." (PMID 26822383, 2016). "Secondly, we assessed activation of each T-lymphocyte clone in response to melanoma cell lines treated +/− IFNγ, by measuring TNFα secretion." (PMID 26885372, 2016). "For example, in a mouse model of melanoma, tumor-infiltrating lymphocytes developed TLOs and displayed clonal expansion of T cells that are reactive to tumor antigens on melanoma cells and inhibit tumor growth through the release of IFNγ." (PMID 27752256, 2016). "Upregulation of CEACAM1, induced by IFNγ on melanoma cells that survive TIL-mediated attack, renders these cells even more resistant." (PMID 27642217, 2016). "In the same work, induction of these co-inhibitory pathways in the tumor microenvironment required the presence of CD8+ T cells and interferon gamma expression in a murine melanoma model." (PMID 26041877, 2015). "We demonstrated that IFNγ secreted by GM-ADSCs is able to directly affect melanoma cells in vitro, probably through activation of JAk1/Stat1 pathway." (PMID 25428727, 2014). "IFNγ inhibited melanoma cell growth in vitro probably via IFNγ-induced JAK/STAT1 signaling pathway activation." (PMID 25428727, 2014). "Our data demonstrates there was increased amount of T CD8 IL-10+ lymphocytes and IFNγ MIF when mice with melanoma were treated with BMDCs stimulated with GK-1 and loaded with MAGE-AX." (PMID 25759825, 2014). "In vivo optical imaging of mice with subcutaneous melanoma revealed a statistically significant reduction of melanoma tumor growth detected by red fluorescent signal in groups co-injected with IFNγ-expressing ADSCs (ANOVA, P < .001)." (PMID 25428727, 2014). "To evaluate the effect of IFNγ on the proliferation of melanoma cells we incubated B16F10 cells with 100 μl of culture medium (CM) supernatant from IFNγ-ADSCs." (PMID 25428727, 2014). "As a subsequent step, we assessed the potential of IFNγ on apoptosis of melanoma cells using Annexin V apoptosis assay." (PMID 25428727, 2014). "IHC analysis of melanoma metastases using a monoclonal anti-mouse IFNγ Ab showed ~4.7 of IFNγ-positive cells per 1000 melanoma tumor cells." (PMID 25428727, 2014).
melanoma (continued). "The results demonstrated that a 48 h incubation of melanoma cells with either WT-ADSC or TRAIL-ADSC in the presence of IFNγ reduced the melanoma cell numbers (ANOVA, P < .001)." (PMID 25428727, 2014). "Immunostaining of pulmonary tumor sections revealed that injected IFNγ-producing ADSCs upregulate PD-L1 expression in melanoma lung tumor cells (compared to metastatic tumor samples from mice that received EGFP-ADSCs or remained untreated)." (PMID 25428727, 2014). "Both melanoma-specific CTL clones tested were found to release increased levels of IFNγ after being co-cultured with DCs preincubated with H-1PV-infected SK29-Mel-1 or HLA-negative SK29-Mel-1.22 cells." (PMID 24822170, 2014). "The analysis of the visible luminescence signal intensity clearly demonstrated IFNγ-induced Jak/STAT-mediated signal activation in ISRE/FL-melanoma cells." (PMID 25428727, 2014). "Of note, we did not detect substantial differences with day 14 γδT cells derived from either healthy individuals or melanoma patients in their potencies to induce intracellular IFNγ responses." (PMID 25101086, 2014). "Recombinant mouse IFNγ was used to evaluate the effect of purified IFNγ on the proliferation of melanoma cells." (PMID 25428727, 2014). "More importantly, intravenously injected IFNγ-ADSCs significantly reduced growth of pre-established melanoma lung metastases." (PMID 25428727, 2014). "Ability of TILs from the primary B16 tumor to kill B16 melanoma cells and release IFNγ in vitro was higher in the treated versus untreated animals." (PMID 24949488, 2014). "There was no additive effect on tumor ablation when IFNγ/TRAIL-ADSCs were co-injected with the melanoma cells, indicating that presence of IFNγ is solely responsible for tumor reduction." (PMID 25428727, 2014). "Following 20 days of expansion, TIL grown after feeder cell stimulation in plates and in bags were tested for their ability to produce IFNγ in response to autologous melanoma cell line stimulation." (PMID 21575188, 2011). "By studying the reactivity of TIL to the autologous melanoma cell lines via IFNγ production, we also found that bags expand a significantly greater quantity of reactive CD8+ T lymphocytes than plates." (PMID 21575188, 2011). "Each individual TIL culture is screened for tumor specific reactivity by coincubation of TIL with autologous melanoma cells over night, followed by the measuring of IFNγ levels." (PMID 21234353, 2010). "Therapy with human lymphoblastoid interferon HuIFN-alpha(N1), or recombinant human interferon gamma, rHuIFN-gamma, inhibited experimental pulmonary metastases of the human melanoma cell line, DX3-azac, in BALB/c nude mice and significantly prolonged survival." (PMID 2460119, 1988). "The tumour immune microenvironment in mucosal melanomas also shows reduced immune cell infiltration and a weaker interferon-gamma signature compared with cutaneous melanoma—a difference that is especially marked in urogenital tumours compared with those of the head and neck." (PMID 41295253, 2025). "Indeed, we found Ceacam1 gene expression to be upregulated in 1205Lu and WM793 after IFNγ treatment, a finding that suggested a possible existence of an alternative mechanism of melanoma resistance formation to NK‐cells." (PMID 41078003, 2025). "PD-L1 is well reported to be induced by interferon gamma signaling in melanoma cells." (PMID 41271007, 2025). "Apart from DCs, melanoma cells were predicted to be the only cells receiving IFNγ signals." (PMID 41078003, 2025). "We validated these findings by exposing melanoma cells to IFNγ and after NK‐cell co‐culture." (PMID 41078003, 2025). "We therefore investigated whether the HH/GLI signaling pathway also contributes to IFNγ/STAT1 regulated IDO1 expression in melanoma." (PMID 39962447, 2025). "However, the presence of the IFNγ‐blocking antibody caused a significant recovery of both the 1205Lu and WM792 melanoma cell susceptibility to NKmK." (PMID 41078003, 2025).
melanoma (continued). "Other studies demonstrated that melanoma cells could upregulate PD-L1 in response to interferon-gamma (IFN-γ) released by activated T cells, effectively dampening the immune response." (PMID 39857682, 2025). "Focusing on the NK‐cell–melanoma interaction, we identified three primary regulatory mechanisms: IFNγ, a cytokine secreted by NK‐cells that plays a crucial role in modulating melanoma cell responses, as well as CD99 and CRTAM, two surface proteins involved in cell adhesion." (PMID 41078003, 2025). "By releasing IFNγ and cytolytic granules, γδ T cells can kill myeloma cells, recognized through ICAM-1 and mevalonate pathway metabolites on the surface, while the majority of melanoma-infiltrating γδ T cells is able to kill cancer cells by producing IFNγ and TNF-α." (PMID 40422223, 2025). "Our current study enhances the understanding of melanoma cell resistance to NK‐cell cytotoxicity by demonstrating that resistance to NKmK is induced by IFNγ‐mediated interactions between melanoma and NK‐cells, with IFNγ, CIITA, and MHC II playing central roles." (PMID 41078003, 2025). "In addition, RT‐qPCR analyses of IFNγ‐exposed melanoma cells revealed upregulated expression of CIITA and several MHC II‐related genes (DR‐A, DQ‐A, DP‐A)." (PMID 41078003, 2025). "Moreover, melanoma patients with high early on-treatment tumour IFNγ scores despite low baseline values still achieved pathological responses after neoadjuvant ICI." (PMID 41291768, 2025). "In addition to decreased cytolytic capacity, splenic NK cells were less able to produce IFNγ in obese mice after FV infection, which is also seen in obese mice challenged with melanoma cells or NK cells from diffuse large B cell lymphoma patients." (PMID 40352719, 2025). "Indeed, high IFNG and IFNG-related gene signatures in patients with different primary and metastatic tumors (i.e., melanoma, head and neck squamous cell carcinoma, gastric cancer, lung cancer) were associated with effective ICI treatments." (PMID 41148229, 2025). "This was true for control as well as IFNγ‐treated melanoma cells." (PMID 41078003, 2025). "Additionally, RT-PCR analysis showed that Jurkat cells co-cultured with Vin-treated melanoma cells exhibited significantly higher mRNA levels of IFNγ, GZMB, IL-2, and TNFα in the activated state." (PMID 40866941, 2025). "Here, we show a relevance of lncRNA GRASLND in melanoma differentiation and IFNγ signaling." (PMID 39398277, 2024). "Our results thus provide a rationale that differentiation may serve as proxy for IFNγ responsiveness in melanomas." (PMID 39736644, 2024). "The results suggested that interferon-gamma (IFNγ) released from T cell immunosurveillance stimulated STAT3-dependent MYC upregulation in melanoma cells, which subsequently activated genes involved in glycolysis and oxidative phosphorylation while suppressing IFNγ-induced cellular senescence." (PMID 38390324, 2024). "Tumor-intrinsic IFNγ signaling has previously been shown to be required for antitumor immune responses in carcinogen-induced mouse models of cancer and responses to immunotherapy in melanoma." (PMID 38635884, 2024). "Overall, these results indicate that dedifferentiated melanoma cells have a widely enhanced response to IFNγ compared to their differentiated counterparts, resulting in greater expression of a multitude of immunologically relevant genes that are not exclusive to the IFNγ response." (PMID 39736644, 2024). "SiRNA mediated MITF knockdown in 624Mel melanoma cells in combination with IFNγ (5 ng/mL) treatment significantly increased PD-L1 expression at both the RNA (one-way ANOVA, P < 0.01) and protein levels (one-way ANOVA, P < 0.001) compared to the expected increase caused by IFNγ treatment alone." (PMID 39736644, 2024). "Together, these findings indicate the existence of a molecular context linking dedifferentiation and IFNγ signaling in melanoma which may lead to immune evasion." (PMID 39736644, 2024).